IL37 (interleukin 37)
Diseases named in the same sentence as IL37 in open-access papers (continued):
Sharing a sentence is not in itself a finding about the gene and the disease.
tumor (continued). "Depending on its localization in the tumor mass, IL-37 acts in different manners: high levels in peritumoral tissues, low levels in the tumor core, where it suppresses the production of IL-6 and β-catenin." (PMID 34944856, 2021). "The expression level of IL37 in the tumor was significantly higher than that in the normal tissues, while SLC5A5, NR4A3, and ODF3L1 were highly expressed in normal tissues than those in tumors." (PMID 34248843, 2021). "IL-6/STAT3 pathway suppression, β-catenin suppression, pSmad3C/P21 tumour-signalling suppression, and CD57+ NK recruitment are said to be the underlying mechanisms for the action of IL-37." (PMID 34336101, 2021). "As the IL-37/IL-37R signaling axis is upstream of MARCO-mediated tumor promotional programs of TAMs, it represents a therapeutic target for repolarization." (PMID 33924237, 2021). "In a human HCC cell line, transfected IL-37 directly targets pSmad3L/c-myk signaling to suppress oncogenic pSmadL signaling and to promote tumor-suppressive pSmad3C signaling." (PMID 33746950, 2021). "In hepatocellular carcinoma patients, increased expression of IL-37 within the tumor environment was resulted in increased infiltration of CD57+ NK cells into the tumor as well as a better prognosis." (PMID 33815404, 2021). "The results showed that higher expression of IL37 in tumor tissues predicted worse prognosis outcomes." (PMID 34248843, 2021). "MARCO, which becomes upregulated upon IL-37-induced M2 polarization is highly expressed on tumor-promoting macrophages and represents a therapeutic target for repolarization." (PMID 33924237, 2021). "The protective effect of IL-37 against various cancer types depends on tumor type and stage and IL-37 isoforms." (PMID 34248996, 2021). "In our previous studies, we found that IL-37 is a potential novel tumor suppressor by inhibiting IL-6 expression to suppress STAT3 activation and decreasing epithelial-to-mesenchymal transition." (PMID 33489865, 2020). "Reduced IL-37 expression in PDACs was associated with increased PDAC histological grade, tumor size, lymph node metastasis and vessel invasion." (PMID 32226541, 2020). "Our data indicated that the IL-37 mRNA was also remarkably decreased in tumor tissues when compared with adjacent tissues (P < 0.01)." (PMID 32226541, 2020). "IL-37 inhibits tumor progression through adaptive antitumor immunity and multiple tumor-suppressive signaling pathways." (PMID 32226541, 2020). "Next, we used 10 paired PDAC specimens including tumor tissues and adjacent tissues to examine the expression of IL-37 mRNA." (PMID 32226541, 2020). "The data showed that IL-37 was drastically lower in serum and tumor specimens with PDAC patients than with healthy people and adjacent normal pancreatic tissues." (PMID 32226541, 2020). "We found that a decrease in IL-37 expression level is closely related to the occurrence and development of NSCLC and that increased tumor malignancy is associated with a more significant decrease in IL-37 expression." (PMID 33489865, 2020). "The combination treatment also significantly increased apoptosis when compared to single treatment, suggesting that IL-37 was able to sensitize anti-tumor efficacy of Gem (P < 0.05)." (PMID 32226541, 2020). "Recently, IL-37 has been described to exhibit anti-tumor activity through chemo-attraction of CD57+ natural killer (NK) cells, inhibiting HCC development." (PMID 31073186, 2019). "IL-37 expression positively correlated with the density of tumor infiltrating CD57+ NK cells in HCC tumors, which were significantly associated with better overall survival in HCC patients." (PMID 31231372, 2019). "For instance, IL-37 reduces the secretion by both immune cells and tumor cells of IL-6, IL-1β and tumor necrosis factor alpha, cytokines known to play a role in tumor progression." (PMID 31231372, 2019).
tumor (continued). "While the JNK/pSmad3L/c-Myc pathway is associated with tumor growth during HCC, the signaling depending on IL-37 diverts pSmad3L from that platform and associates it with the suppressor of tumor p21 in a pSmad3C/p21 complex." (PMID 31507607, 2019). "In HCC model of mice overexpressing IL-37, delayed tumor growth was observed and more NK cells were recruited to tumor tissue." (PMID 29805973, 2018). "IL-37 was hence able to suppress the SMAD signaling pathway tumor cell proliferation and invasiveness via competitive binding to SMAD3." (PMID 29641433, 2018). "The study recognized that a greater IL-37 expression within the tumor microenvironment had a strong positive correlation and better prognosis translated in terms of increased overall survival (OS) as well as disease free survival." (PMID 29641433, 2018). "In tumor tissues, expression of IL-37 was positively correlated with the density of CD57+ natural killer (NK) cells." (PMID 29805973, 2018). "Compared with control group, tumor growth was slower in mice expressing IL-37, possibly related to its inhibitory effects on proinflammatory response and tumor angiogenesis." (PMID 29805973, 2018). "In the present study, data showed that the IL-37 was highly expressed in tumor paired normal tissues and the expression was decreased in cancer tissues." (PMID 28467774, 2017). "Recently, three previous studies demonstrated that IL-37 play a protective role in tumor progression." (PMID 26791086, 2016). "Mechanistically, we determined that IL-37 promoted Smad3 phospho-isoform signaling conversion from JNK/pSmad3L/c-Myc oncogenic signaling to pSmad3C/p21 tumor-suppressive signaling." (PMID 27835881, 2016). "Specifically, 76 of 182 tumor tissues (41.7 %) and 106 of 182 normal tissues (58.2 %) had a high level of IL-37 expression (P < 0.01)." (PMID 26791086, 2016). "Previous study also showed that IL-37 mediated anti-tumor immune responses through recruiting NK cells to tumor microenvironment in HCC." (PMID 26791086, 2016). "Functional studies further showed that IL-37 overexpression significantly suppressed tumor growth by confining HCC to G2/M cell cycle arrest in vitro and in vivo." (PMID 27835881, 2016). "Compared with the adjacent non-tumor liver tissues (ANLTs), significantly lower expression of IL-37 mRNA was observed in 85.15% (86/101) of HCC samples, suggesting that reduction of IL-37 was a frequent event in human HCC." (PMID 27835881, 2016). "IL-37 has been characterized as a fundamental inhibitor of innate immunity and a tumor suppressor in several cancers." (PMID 27835881, 2016). "The anti-tumor effect of IL-37 results from the suppression of tumor-promoting cytokines, such as IL-1β, which activates IL-6 and TNF, direct effects on tumor cells, and reduction of cell proliferation by interfering with NF-κB, MAPK, and signal transducer and activator of transcription 3 (STAT3)." (PMID 41596472, 2026). "We discuss how IL-37 can modulate these processes in different contexts-sometimes impeding tumor growth and other times facilitating it-depending on factors including the tumor type, stage, and surrounding microenvironment." (PMID 42238575, 2026). "Moreover, transgenic mice possessing human IL-37 genes have the ability to reject tumor cells, and overexpression of this cytokine in some tumors leads to better overall survival." (PMID 41596472, 2026). "Additionally, IL-37 indirectly impedes tumor cell migration by modulating the Rac1 signaling pathway." (PMID 41293155, 2025). "In cancer, IL-37 may influence the tumour microenvironment and has been reported to suppress tumour growth under certain conditions." (PMID 40777036, 2025). "Furthermore, IL-37 significantly inhibits tumor cell proliferation, metastasis, and angiogenesis, highlighting its value in NSCLC immunotherapy." (PMID 41293155, 2025). "IL-37, an anti-inflammatory cytokine, suppresses tumour growth." (PMID 40191189, 2025).
tumor (continued). "This complex role of IL-37 may be related to its microenvironment; it mainly exerts an inhibitory effect in the tumor microenvironment, but tends to promote angiogenesis under specific pathological conditions such as hypoxia." (PMID 41293155, 2025). "Interestingly, in most other cancers examined to date, elevated levels of IL-37 have correlated with anti-tumor activity and with improved survival." (PMID 39206201, 2024). "The differing functions of IL37 in various tumours may be attributed to the varying sensitivity of different tumour types to IL37, highlighting the complexity of IL37's role in cancer." (PMID 39500733, 2024). "Therefore, future investigations should consider using humanized animals or immunocompetent hosts with human HCC cells or manipulated IL-37 (knockout or transgenic) animals to verify the anti-tumour function in vivo." (PMID 38312834, 2024). "Considering the high expression of IL37 in OSCC tumour cells, we hypothesized that the abnormal expression of IL37 might have functional significance for the tumour cells themselves." (PMID 39500733, 2024). "Interestingly, when examining the expression of intrahepatic IL-37 in adjacent non-tumour tissues, a significant difference in IL-37 levels was observed between male and female HCC patients." (PMID 38312834, 2024). "IL-37 enhances the expression of antiangiogenic factors while concurrently reducing the expression of proangiogenic factors by tumour cells, thereby inhibiting tumoral angiogenesis within the tumour microenvironment." (PMID 38312834, 2024). "We hypothesized that the upregulation of IL37 in OSCC could be a means of self‐protection for tumour cells against the inflammation induced by the hypoxic tumour environment." (PMID 39500733, 2024). "Moreover, our study revealed that IL37 was not only highly expressed within tumour cells but also in the extracellular matrix." (PMID 39500733, 2024). "Specifically, it is concluded that IL-37 can inhibit the growth and migration of tumor cells, prohibit angiogenesis and mediate the immunoregulation in tumor microenvironment, so as to exert effective anti-tumor effects." (PMID 37928545, 2023). "Furthermore, IL-37 was reported to protect HCC cells against tumor progression by activating immunity in TME via regulating NK cells." (PMID 37928545, 2023). "This is the first time, to the best of our knowledge, that IL-37 and SIGIRR levels have been assessed in BLCA tumor lesions, and associations with pathological and survival parameters are described, while a transcript variant-specific signature is indicated to have a diagnostic potential." (PMID 37298214, 2023). "The data from the research explained that IL-37 exerted a significant role in the connection between innate and adaptive immunity, and may be a promising candidate for tumor immunotherapy." (PMID 37928545, 2023). "Interestingly, in endometrial cancer cells both Rac1—an indicator of tumor cell migration and invasion, and MMP-2—an indicator of tumor metastasis and primary tumor growth—were downregulated by IL-37." (PMID 36769226, 2023). "Similarly, a high prevalence of IL-37+CD1a+ DCs in HCC tumor infiltration is a marker of favorable prognosis of patients." (PMID 37298214, 2023). "Various tumor cells were also reported to express angiogenesis factors under the hypoxic condition to favor tumor progression, such as IL-6, MMPs, VEGF and hypoxia-inducible factor (HIF)-1α, and IL-37 treatment was proven to prevent tumor cells from producing such factors." (PMID 37928545, 2023). "Moreover, IL-37 reduces tumor promoting cytokines including IL-6, IL-1β and TNF-α produced by both tumor cells and immune cells." (PMID 37928545, 2023). "In conclusion, our finding identified a novel regulatory mechanism of IL‐37 in tumor immunity." (PMID 36891351, 2023).
tumor (continued). "Our research results suggest that the mechanism by which IL‐37 acts on CD103+DCs may represent a potential target for the clinical development of anti‐tumor drugs for patients with SCC." (PMID 36891351, 2023). "The contribution of myeloid dendritic cells (mDCs) within tumor-association infiltration was of similar levels in patients with and without IL-37 non-synonymous mutations (log2fold-change = 1.171, p = 0.047)." (PMID 36551790, 2022). "Moreover, the expression profiles of IL-37 and SIGIRR are associated with LUAD development and tumor stage, whereas their high mRNA levels are favorable prognostic factors for the overall survival of patients." (PMID 36551790, 2022). "We, therefore, correlated IL-37 serum level with CD8+ tumor-infiltrating lymphocytes to determine whether IL-37 expression could predict cytotoxic T cell potential." (PMID 35046386, 2022). "Single-cell analyses supported their expression by lung tissue-resident T cells and ΜΦ, but relevant study should also be applied in LUAD tumor biopsies to explore the possible inducible expression of IL-37 isoforms and SIGIRR by malignant epithelial and/or tumor-infiltrating immune cell subsets." (PMID 36551790, 2022). "Our results also reveal the prognostic potential of tumor-expressed IL-37 and SIGIRR patterns." (PMID 36551790, 2022). "On the contrary, IL-37 could significantly inhibit the proliferation and invasion of tumor cells in PCa." (PMID 36237303, 2022). "We utilized a series of bioinformatics tools and -omics datasets to unravel possible associations of IL-37 and SIGIRR expression levels and genetic aberrations with tumor development, histopathological parameters, distribution of tumor-infiltrating immune cells, and survival rates of patients." (PMID 36551790, 2022). "Thus, the high expression of IL-37 in specific lymphocyte populations can be considered as a biomarker for immunosuppression induced by tumor." (PMID 34248996, 2021). "Furthermore, IL-37 exerts an inhibitory effect on tumor angiogenesis and metastasis, and progression." (PMID 34248996, 2021). "However, the opposite effect is observed when HUVECs are treated with the supernatant from tumor cell lines overexpressing IL-37, since they undergo apoptosis and their migration and tubule formation is suppressed." (PMID 34248996, 2021). "A study recently found that IL-37 demonstrates a protective role in cancer development possibly through tumor angiogenesis and that it could serve as a promising therapeutic target for NSCLC." (PMID 34805976, 2021). "Indeed, IL-37 overexpression in HCC cells is related with the recruitment of more DCs into the tumor tissues by secreting high levels of specific chemokine, such as CCL3 and CCL20, significantly reducing tumor growth." (PMID 34248996, 2021). "In addition, the expression of IL-37 in liver cancer tissues is also decreased, and its expression level is negatively correlated with tumor size." (PMID 33224886, 2020). "Previously, it has been reported that IL-37 suppresses tumor growth and progression." (PMID 32226541, 2020). "Intracellular mature IL-37 suppresses tumor metastasis via inhibiting Rac1 activation." (PMID 32226541, 2020). "Given broad regulatory roles of IL-37 in cell growth, we hypothesized that IL-37 confers anti-tumor activity through regulation of m6A methylation." (PMID 33489865, 2020). "Further studies are needed to clarify whether IL-37 has direct tumor suppressing properties or rather acts indirectly by modulating inflammation." (PMID 31781119, 2019). "IL-37 has also been shown to affect immune cell recruitment to the tumor microenvironment." (PMID 31231372, 2019). "Furthermore, similarly administered multiple doses of IL-37 gene completely halted tumor development." (PMID 29641433, 2018).
tumor (continued). "It is speculated that IL-37 may rely on different pathways in different tumors to achieve its function, for example, by enhancing the function of effector T or altering the tumor microenvironment to achieve antitumor effects." (PMID 29805973, 2018). "It is speculated that IL-37 may inhibit tumor angiogenesis and thus play a role in tumor suppression." (PMID 29805973, 2018). "But in the peri-tumor tissues, IL-37 would suppress the immune system." (PMID 28467774, 2017). "The promoting effect of CTCs on tumor cell metastasis could be abrogated by suppressing inflammatory response with IL-37, an anti-inflammatory cytokine, or blocking CTC-derived ligands for TLR2/4." (PMID 28415700, 2017). "For this purpose, we expressed IL-37, an anti-inflammatory cytokine that suppresses the expression of multiple pro-inflammatory cytokines and may also has an anti-tumor effect, in B16F1-inoculated mice." (PMID 28415700, 2017). "To exclude the possibility that IL-37 may have a direct effect on tumor cells, we tested the effect of IL-37 on tumor cell proliferation and colonization." (PMID 28415700, 2017). "In support of cell-based findings, we also found a significant negative correlation between intratumoral IL-37 expression and tumor angiogenesis measured as CD34-determined intratumoral MVD in human NSCLC samples, suggesting an inhibitory role of IL-37 in the tumor angiogenesis." (PMID 26791086, 2016). "However, low IL-37 expression was significantly correlated with higher tumor status (P = 0.017) and advanced TNM stage (I-II versus III, P = 0.000)." (PMID 26791086, 2016). "Collectively, these results suggest that IL-37 may contribute to the suppression of tumour metastasis." (PMID 27225603, 2016). "Very recently, it has been demonstrated that IL-37 not only affects anti-inflammatory responses, but could also play a protective role in tumor progression." (PMID 27835881, 2016). "IL-37 mRNA and protein expressions were significantly decreased in NSCLC tissues, and decreased intratumoral IL-37 expression was significantly associated with tumor state, TNM stage and poor prognosis in NSCLC patients." (PMID 26791086, 2016). "Moreover, IL-37 promoted Smad3 phospho-isoform signaling conversion from JNK/pSmad3L/c-Myc oncogenic signaling to pSmad3C/p21 tumor-suppressive signaling." (PMID 27835881, 2016). "In HCC tumor tissues, there was variation in the level of IL-37 expression." (PMID 27835881, 2016). "This suggests that IL-37 may contribute to tumour suppression by enhancing NK cell recruitment." (PMID 40191189, 2025). "Interestingly, an analysis performed in vitro proclaimed that the direct effect of rIL-37 on human umbilical vascular endothelial cells (HUVECs) was proangiogenic, but supernatants derived from IL-37 overexpressed tumor cell lines switched its function to anti-angiogenesis." (PMID 37928545, 2023). "Lastly, high levels of IL-37 secreted by peripheral blood Tregs of individuals with melanoma reflect the secretion of TGFβ and other IL-1β mediators by the tumor, thus indicating it could be interpreted as a potential marker for immunosuppression induced by the tumor." (PMID 37298214, 2023). "It is interesting that in CRC patients, serum IL-37 levels are increased and associated positively with the serum levels of CEA (carcinoembryonic antigen), a widely-used biomarker for CRC diagnosis and monitoring, and negatively with the infiltration rates of CD8+ T cells in the tumor." (PMID 37298214, 2023). "What is more, IL-37 correlates positively with a LUAD-associated transcriptomic signature, and its nucleotide changes and expression levels are linked with distinct infiltration patterns of certain cell subsets known to control LUAD anti-tumor immune responses." (PMID 36551790, 2022).